TNF (tumor necrosis factor)
Diseases named in the same sentence as TNF in open-access papers (continued):
Sharing a sentence is not in itself a finding about the gene and the disease.
bacterial infection (continued). "Bacterial infection led to a significant increase in the levels of pro-inflammatory factors, such as TNF-α, Il-1ꞵ, and IL-6, while the level of the anti-inflammatory factor IL-10 decreased." (PMID 40713896, 2025). "It is well-known that wound bacterial infection enhance excessive inflammatory cell infiltration with subsequent release of several pro-inflammatory cytokines/mediators as TNF-α and PGS-2." (PMID 40100378, 2025). "Following a bacterial infection, various cells in the body, such as macrophages and monocytes, quickly release numerous cytokines, including TNF-α, that trigger an inflammatory response in the host." (PMID 41357523, 2025). "Viral and bacterial infections increase expression of TNF-α, IL-1β, and other cytokines that stimulate NF-kB activation responsible for amplifying and driving expression of downstream cytokines/chemokines such as CXCL5." (PMID 40494897, 2025). "Delayed wound healing can be attributed to a widespread inflammatory response primarily driven by bacterial infection, leading to failed macrophage polarization and excessive secretion of inflammatory factors such as TNF-α, IL-6, and IL-1β." (PMID 40051835, 2025). "TNF-α inhibitors interfere with immune cell activation, proliferation, and inflammatory cytokine production-in the context of bacterial infection, this includes impaired macrophage activation and neutrophil recruitment." (PMID 41531628, 2025). "In response to bacterial infections, pro-inflammatory cytokines including IL-8, IL-6, TNF-α, and IL-1β are released, triggering neutrophil recruitment and new neutrophil production via G-CSF." (PMID 40766078, 2025). "Common interleukins released by keratinocytes during bacterial infections include IL-1α, IL-6, IL-36, and TNF-α." (PMID 40856949, 2025). "In the Drosophila innate immunity, Toll and Imd pathways are essential for host defense against fungal and bacterial infections, which share similar functions with the mammalian TLRs and TNF signaling pathways." (PMID 39833169, 2025). "Collectively, IL-10 and TNF-α form a critical immune regulatory pathway against bacterial infections." (PMID 41463795, 2025). "The data presented in this study suggests intricate immune modulation of macrophage responses to bacterial infections, particularly in relation to TNF-α, IL-6, IL-10, and IL-12A cytokine profiles." (PMID 40873569, 2025). "In rat serum, IL-1β, IL-6, and TNF-α levels were significantly elevated, and increased internal bacterial infection and toxins were detected, implicating internal bacterial infection and toxin release as major factors in increased mortality after RCI." (PMID 41226494, 2025). "HnRNPs regulate innate as well as adaptive immunity in response to bacterial infections such as HnPNPA0 binds to specific sequence of inflammatory genes including TNF-α and IL-6, controlling the inflammatory response." (PMID 41026719, 2025). "TNF-α is an important inflammatory cytokine that plays a key role in the body’s immune response, especially against bacterial infections." (PMID 41357523, 2025). "Intramuscular iron supplementation alleviated the clinical symptoms of bacterial infection, decreasing the diarrhea rate by 53% and mitigating the inflammatory response with lower serum levels of pro-inflammatory cytokines, such as TNF-α, IL-6, and IL-8." (PMID 40746956, 2025). "Cytokines such as TNF-α, IL-6, and IL-10, released during viral or bacterial infections, bind to specific receptors on C-fiber neurons of the vagus nerve, causing depolarization and increased excitability." (PMID 41044788, 2025). "Some studies demonstrated up-regulated expression of TNF-α in vivo after stimulation with different bacterial infections in the early inflammation stage." (PMID 41012187, 2025). "TNF-α, a cytokine activated by nuclear factor-kappa B (NF-κB), plays a crucial role in the immune response to periodontopathogenic bacterial infections and bone resorption." (PMID 40863063, 2025).
bacterial infection (continued). "In bacterial infections, a CARD9 deficiency results in a decrease in inflammatory cytokines (IL-1β, IL-6, and TNF-α) and chemokines (CXCL1, CXCL2, and CXCL5)." (PMID 38473845, 2024). "Tumor necrosis factor-α (TNF-α) is a pleiotropic pro-inflammatory cytokine induced by bacterial infections." (PMID 37855658, 2024). "IL-6 and TNF-α are inflammatory markers frequently produced in response to tissue injury and bacterial infections." (PMID 39415253, 2024). "Similar to the results of bacterial infection, IL-6 or TNF-α production in response to PAMP ligands was significantly increased in DDX5-deficient Mø." (PMID 38182816, 2024). "TNF-α is considered a master regulator of inflammatory cytokine cascade in immune responses playing a protective role against viral, protozoan, or bacterial infection and other inflammatory diseases." (PMID 39125036, 2024). "The intensities of inflammatory indicators, like IL-1β, IL-6, and TNF-α, usually rise during bacterial infections as they are part of bacterial pathogenesis." (PMID 39338376, 2024). "TNF refers to tumor necrosis factor, which is a cytokine naturally produced by macrophages in response to a bacterial infection or other immunogenic reactions." (PMID 39682940, 2024). "In summary, we found Tim3 to be a biomarker of TNF signaling in NK cells, and this signaling pathway as a major regulator of NK cell-mediated immunity during bacterial infection." (PMID 39543125, 2024). "Within a few hours of contracting a bacterial infection, children emit huge amounts of interleukins and tumor necrosis factor, which will boost the expression of PCT gene." (PMID 39048958, 2024). "In this study, we have found TNF signaling is a major regulator of NK cell function during bacterial infection." (PMID 39543125, 2024). "Among systemic treatments, bacterial infections were more frequent in users of TNF‐α and IL‐17 inhibitors." (PMID 38660962, 2024). "TNF-α prevents several bacterial infections; however, the action of TNF-α is impaired during acute exposure to alcohol." (PMID 38665743, 2024). "More research is required to fully appreciate how TNF impacts NK cell function across different contexts, including bacterial infection." (PMID 39543125, 2024). "TNF-α is produced by macrophages and phagocytes in response to bacterial infection or other immunogenic reactions and promotes cell proliferation and differentiation." (PMID 39272296, 2024). "In particular, the clavanin-MO peptide (used at 2 μM) promoted the synthesis of the anti-inflammatory cytokine IL-10 while suppressing the release of the pro-inflammatory factors IL-12 and tumor necrosis factor-α (TNF-α) upon bacterial infection." (PMID 39057413, 2024). "In the presence of bacterial infection, serotonin plays a role in inhibiting the production of TNF-α stimulated by LPS and increasing the release of IL-1β by peripheral blood mononuclear cells." (PMID 38998045, 2024). "The NET-array device developed and validated in this study, enabled the quantification of increased NET release to Pseudomonas aeruginosa PAO1 bacterial infection in microenvironments rich in inflammatory cytokines, TNF-α and IL-6." (PMID 38189525, 2024). "In bacterial infection, inflammatory cytokines (such as tumor necrosis factor-alpha, IL-1β, and IL-6) induce gene expression responsible for PCT production." (PMID 38698211, 2024). "Activation of TLR2/4 can induce NF-κB-regulated inflammatory cytokines, such as interleukin 6 (IL-6) and tumor necrosis factor-alpha (TNF-α) during bacterial infection." (PMID 38182816, 2024). "As model biomarkers we chose three cytokines (interleukin-6, interleukin-8, tumor necrosis factor alpha), the bacterial infection marker C-reactive protein and the bacterial pathogen Streptococcus pneumoniae—all relevant factors in exacerbation episodes." (PMID 38834656, 2024).
bacterial infection (continued). "Th1 cells produce cytokines such as interferon (IFN)-γ, interleukin (IL)-2 and tumor necrosis factor (TNF) to prevent intracellular bacterial infection and delayed hypersensitivity." (PMID 38972998, 2024). "In pregnancy, the inflammatory and bacterial infection processes lead to the production and release of proinflammatory cytokines such as tumoral necrosis factor alpha (TNF-α) and interleukins (ILs) (IL-1,IL-2,IL-3,IL-4,IL-6,IL-7,IL-8,IL-10)." (PMID 39274519, 2024). "Taken together, these data demonstrate that DDX5 blocks IL-6 or TNF-α synthesis during bacterial infection in vitro and in vivo." (PMID 38182816, 2024). "Upon recognition of foreign nucleic acid molecules, PRRs stimulate especially inflammatory cytokines interleukin 6 (IL-6) and tumor necrosis factor alpha (TNF-α), and ultimately induce cellular apoptosis to prevent the spread of viral and bacterial infections." (PMID 37111695, 2023). "Under conditions of cellular stress, such as the presence of reactive oxygen species (ROS), Tumor necrosis factor (TNF-α), proinflammatory cytokine interleukin 1β (IL-1β), viral and bacterial infections, etc., sphingomyelinase becomes activated." (PMID 37333888, 2023). "The inflammatory factors associated with bacterial infection of IFN-γ, TNF-α, IL-1α, and IL-6 were measured by ELISA analysis." (PMID 36937280, 2023). "This study was performed to understand the glucocorticoid receptor's (GR's) effects on chemokine and acute-phase protein expression in human liver, in settings of bacterial infection (modeled using LPS) or inflammation (modeled using TNFα)." (PMID 39619227, 2023). "Among PGES, mPGES-1 is an enzyme induced by the stimulation of inflammatory mediators such as IL-1β and TNF-α, mainly released by macrophages after tissue damage or bacterial infection." (PMID 36661522, 2023). "Preadipocytes respond to bacterial infections by producing and releasing proinflammatory cytokines such as TNF-α, IL-6, and IL-8, which trigger inflammation and attract immune cells to the affected area." (PMID 38111581, 2023). "To determine the regulation of chemokine expression in PHH, we compared the effects of DEX on PHH in the setting of generic inflammation versus bacterial infection, mimicked by the treatment with TNFα and LPS." (PMID 39619227, 2023). "Macrophages play a critical role in fighting bacterial infections by phagocytosis, and possess a specific role in immune regulation by secreting pro-inflammatory cytokines, such as IL-6 and TNF-α." (PMID 36846783, 2023). "Hepatocytes, by producing IL-1β, IL-6, and tumor necrosis factor (TNF-α) in response to stimulation by bacterial infection, lipopolysaccharides (LPS), hepatocyte growth factor (HGF), H2O2, and TNF-α are a source of inflammatory mediators in the liver." (PMID 37153436, 2023). "In the early stages of bacterial infection, Mφ are classically polarized to the M1 phenotype, which upregulates the expression of classic inflammatory phase markers, namely iNOS, IL-6, and TNF-α." (PMID 37887741, 2023). "Enrichment analysis results suggested that melittin plays an anti-RA role mainly through tumor necrosis factor, interleukin-17, toll-like receptors, and advanced glycation end products–RAGE signaling pathways, and pathogenic bacterial infection." (PMID 37565866, 2023). "Cell death, characterized as programmed (apoptosis) or accidental (necrosis, necroptosis, or pyroptosis), is instigated by factors such as tumor necrosis factor (TNF) or bacterial infection." (PMID 37822610, 2023). "The immune signaling molecule tumor necrosis factor (TNF) is critical for defense against many bacterial infections." (PMID 37279255, 2023). "Taken as a whole, our study deepens our understanding of the mechanisms by which TNF is able to position cells to better control intracellular bacterial infection." (PMID 37279255, 2023). "TNF is a pleiotropic cytokine that participates in several inflammatory processes, including bacterial infections, such as TB." (PMID 38138078, 2023).
bacterial infection (continued). "Although not definitive, the available data indicate that IL-17 and IL-23 inhibitors are less likely to favor bacterial infections than TNF-α blockers." (PMID 38098852, 2023). "KEGG pathway analysis further revealed a strong link to early immune activation and inflammatory response by activating pathways involved in cytokine signaling (such as TNF-α and IL-17 signaling), chemokine signaling, and bacterial infections." (PMID 37694286, 2023). "The cytokines TNF-α, IL-6, IL-12/IL-23 p40, and IL-1β were measured in this experimental set-up as they are highly important for the defense against a bacterial infection: the release of TNF-α increases phagocytic capacities of macrophages." (PMID 37654489, 2023). "TAK981 treatment did not affect blood urea nitrogen but increased the innate immune responses to bacterial infection including serum IFNγ and TNFα levels." (PMID 37520526, 2023). "In our study, compared with healthy pregnant women, we observed a significant increase in IL‐2, IL‐6, IL‐10 and IFN‐γ in pregnant women with both influenza A and bacterial infection but lower levels of TNF‐α in both groups." (PMID 37638092, 2023). "In our longitudinal study, reductions in pro-inflammatory markers (CRP, IL6 and TNFα) and increments in anti-inflammatory markers (IL4) were associated with an improvement in CSDD and MMSE levels in patients recovering from a bacterial infection." (PMID 37762523, 2023). "Inflammatory cytokines such as TNF secreted by bacterial infection promote RANKL, resulting in bone resorption through osteoclast activation." (PMID 36768829, 2023). "Procalcitonin production occurs in response to lipopolysaccharide, bacterial infection, and cytokines including interleukin 6 (IL-6) and tumor necrosis factor alpha (TNF-α)." (PMID 35531376, 2022). "The IL-6, IL-10 and TNF cytokines are produced by activated macrophage cells as a positive response of inflammatory reactions in the process of bacterial infection." (PMID 35369436, 2022). "M1 ΜΦs are activated by viral and bacterial infection, interferon-γ, lipopolysaccharide (LPS), and tumor necrosis factor (TNF), which is known as the classical activation pathway." (PMID 36201245, 2022). "uPAR expression is upregulated on endothelial and hematopoietic cells during bacterial infection and in response to pro-inflammatory cytokines [e.g., tumor necrosis factor alpha (TNF-α), interferon gamma (IFN-γ), and interleukin 2 (IL-2)]." (PMID 35757694, 2022). "Similar to our findings, the levels of pro-inflammatory cytokines, IL-6, TNF-α, and IL-1β, tested after bacteriophage administration, were significantly lower than in the group with developed bacterial infection, treated with PBS alone." (PMID 36211337, 2022). "Their expression levels are dramatically elevated, resulting in an increase in the production of inflammatory cytokines such as IL-1β and TNF-α on bacterial infections in mammals." (PMID 36557603, 2022). "This early elevation of LL-37 plays a role in the control of the detrimental effects of bacterial infection by inhibiting the secretion of TNF α." (PMID 36018845, 2022). "NF-kB is activated in response to viral and bacterial infection stimuli, increased IL-6, IL-8, TNF-α and oxidative stress." (PMID 36560801, 2022). "As well-known inflammatory cytokines or chemokines, TNF-α, IL-1β, IL-6, and IL-8 are involved in various types of inflammatory responses and are crucial in inflammatory processes during bacterial infection in bovine mammary glands." (PMID 35681915, 2022). "Cytokines associated with bacterial infections were downregulated (i.e., IL1β, IL6, IL8, TNFα), whereas the anti-inflammatory cytokine IL10 was upregulated." (PMID 36671404, 2022). "The presence of a bacterial infection, particularly Pseudomonas, will promote the secretion of IL-8 and TNF-alpha, leading to bronchial remodeling." (PMID 35633979, 2022).
bacterial infection (continued). "For EGFR inhibition, the populations of dermal immune cells primarily include macrophages and mast cells; TNF-α secreted by macrophages promotes subsequent epidermal barrier defects and bacterial infections." (PMID 36204127, 2022). "TNF-α is the earliest and most important inflammatory mediator in the response to viral and bacterial infection." (PMID 35722153, 2022). "TNF-α is produced by T cells, B cells, NK cells, and macrophages and regulates inflammation and host defense by inhibiting bacterial infection and acute stress." (PMID 35662944, 2022). "The influence of bacterial infection on immunomodulating molecules (TNFα, MDP, Tri-DAP, SB203580, Cycloheximide) in HMEEC was evaluated." (PMID 35433505, 2022). "HIF-1α is induced by bacterial infection and regulates the production of crucial immune effector molecules, including nitric oxide and TNF-α." (PMID 34898382, 2022). "Increased IL-6, IL-8, IL-10 and TNF-α concentrations have been reported following surgical procedures and in the early stages of bacterial infections both in adults and children." (PMID 36154663, 2022). "IL-17 is induced during bacterial infection, and in turn induces the production of inflammatory cytokines including IL-1, GM-CSF, TNF-α, and IL-6, and chemokines such as MCP-1, MCP-3, and MIP-3A." (PMID 36386225, 2022). "Compared to SARS-P, and in line with results obtained for IL-2 and IFNy, both cohorts with bacterial infection displayed significantly lower TNF levels on all three days." (PMID 36109525, 2022). "Most of these chemokines and cytokines, such as CCL5, CCL22, IL-1β, and TNF-α, are critical to “pre-condition” the lungs to become invulnerable to bacterial infections or promote bacterial clearance during lung infections." (PMID 35677203, 2022). "During inflammatory condition, such as viral or bacterial infection, there comes to a rapid increase of pro-inflammatory markers such as interleukin 4 (il-4), interleukin 6 (il-6), tumor necrosis factor (TNF) and C reactive protein (CRP)." (PMID 35431842, 2022). "NFκB mediates responses to viral and bacterial infections by releasing cytokines, including IL-1β, IL-6, and TNF-α." (PMID 36362264, 2022). "A variety of inflammatory cytokines are sequentially produced after bacterial infection (called the ‘cytokine cascade’), beginning with the production of pro-inflammatory cytokines such as IL-1, TNF-α, and IL-12." (PMID 35628471, 2022). "As a result, the expression of IL-1β and TNF-α proteins stimulated by the bacterial infection was improved following THSG, NAC, and apocynin treatment." (PMID 35453424, 2022). "Collectively, OTUB1 is a hepatocyte-intrinsic factor inhibiting necroptosis upon bacterial infection and TNF-induced liver damage, respectively, thereby, protecting the host from lethal exacerbation of these inflammatory diseases." (PMID 33712742, 2021). "LPS endotoxins are widely used as experimental models of systemic bacterial infection and trigger inflammatory factors such as TNF-α, IL-1β and IL-6." (PMID 33557833, 2021). "TAB1 is part of the TAB1/2/3/TAK1 complex that regulates the activity of TAK1 (TGFβ-activated kinase 1), in response to different stimuli including TGFβ, IL1, TNFα and upon viral and bacterial infections." (PMID 33372854, 2021). "IL-6, IL-1β, and tumor necrosis factor-α (TNF-α) are produced by brain microvascular endothelial cells (BMECs), astrocytes, and microglial cells at the early stages of bacterial infection." (PMID 33808027, 2021). "The trend of IFN‐γ and TNF‐α in this animal model shows that they respond more slowly to bacterial infections than other cytokines." (PMID 34725873, 2021). "In normal physiological conditions, NE as an agonist of α- and β-adrenergic receptors, reduced TNFα expression in monocytes challenged with LPS, implying its anti-inflammatory role in bacterial infections." (PMID 33538227, 2021).